TLR2 (toll like receptor 2)
Diseases named in the same sentence as TLR2 in open-access papers (continued):
Sharing a sentence is not in itself a finding about the gene and the disease.
infection (continued). "Analysis of BAL fluid demonstrated a significant reduction in secretion of TNF in the lungs of TLR2−/− and MyD88−/− mice compared to control mice at 5 days post-infection." (PMID 19936231, 2009). "Infection with the obligate parasite T. gondii has been shown to increase expression of certain TLRs (TLR2, 4, 9 & 11 (murine)) while cold water stress following infection seems to decrease the expression of the same TLRs." (PMID 20011045, 2009). "According to our results, it can be proposed that TLR2 triggering is mostly affecting the direct productive infection of IM-MDDCs with HIV-1 since treatment with EFV reduced the level of viral transfer close to that observed for untreated cells." (PMID 19419540, 2009). "There was a low (<50 copies/per 104 β-actin), but significant upregulation of TLR-1 and TLR-2 in SARS-CoV infected adult DCs at 3 h post infection." (PMID 19505311, 2009). "Although in general the pulmonary concentrations of these mediators were lower in TLR2 KO mice, the differences with WT mice were statistically significant only for KC (P < 0.005 at 24 and 48 h post infection) and IL-1β (P < 0.05 at 48 h)." (PMID 17711480, 2008). "To obtain insight in the growth of S. pneumoniae PLN during the infection (i.e. before the first mice started dying), we infected TLR2 KO and WT mice with S. pneumoniae PLN and determined bacterial loads in whole lung homogenates at 24, 48 and 72 h thereafter." (PMID 17711480, 2008). "The bacterial loads in lungs of TLR2 KO mice and WT mice were similar at this early time point during infection with S. pneumoniae D39 or S. pneumoniae PLN." (PMID 17711480, 2008). "Whereas the bacterial burdens were not significantly different between TLR2 KO and WT mice 24 h post infection, at 48 and 72 h TLR2 KO displayed significantly higher bacterial loads in their lungs than WT mice (both P < 0.05)." (PMID 17711480, 2008). "Although TLR2 KO mice displayed a reduced inflammatory response 6 h after infection with either S. pneumoniae D39 or PLN, some responses were more strongly diminished after infection with the pneumolysin-deficient strain." (PMID 17711480, 2008). "Parameters of lung inflammation in TLR2 KO and WT mice 24 and 48 h after infection with WT S. pneumoniae D39." (PMID 17711480, 2008). "To further investigate the role of TLR2 during infection with S. pneumoniae PLN, we determined TNF-α, IL-1β, IL-10, MIP-2, KC and MPO levels in whole lung homogenates obtained 24, 48 and 72 h after inoculation." (PMID 17711480, 2008). "Role of TLR2 in the early inflammatory response in the lungs after infection with S. pneumoniae D39 or PLN." (PMID 17711480, 2008). "At 24 h post infection, pulmonary cytokine and chemokine levels were lower in TLR2 KO mice, significantly so for IL-1β (P < 0.05)." (PMID 17711480, 2008). "Similar to cytokine and chemokine levels, MPO concentrations were modestly lower in TLR2 KO, significantly so at 48 h post infection (P < 0.01)." (PMID 17711480, 2008). "Nevertheless after 48 h of infection TLR2-/-/CD14-/-mice had higher concentrations of bacteria in both CSF and brain than either TLR2-/-or CD14-/-mice." (PMID 17428319, 2007). "Bacterial load and TNF in TLR2-/-, CD14-/- and TLR2-/-/CD14-/- mice was assessed simultaneously in all knockout mice after infection and values in knockout strains were compared to those in wt mice." (PMID 17428319, 2007). "TNFα and IL6 levels were lower in TLR2 KO mice than in WT mice, especially at 72 h after infection (p < 0.05 and p < 0.001, respectively)." (PMID 17676990, 2007). "Our findings provide new insights into the coordinated roles of TLR2 signaling and the microbiome in controlling infection of mycobacteria via the gut and underscore the importance of TLR2 in macrophage function during mycobacterial gut infection and dissemination." (PMID 42212334, 2026).
infection (continued). "Integrated proteomic and in silico molecular docking analyses revealed favorable binding between punicalagin and several key innate immune proteins upregulated during infection, including Toll‐like receptor 2 (TLR2), its adaptor MyD88, and the cytokine macrophage migration inhibitory factor (MIF)." (PMID 41085014, 2026). "Knockdown of YTHDC2 after TM infection increases TLR2 expression." (PMID 40066451, 2025). "TLR2 also interacts with viral proteins as a TLR2/6 heterodimer, mediating cytokine production during infection with some strains of lymphocytic choriomeningitis virus (LCMV), New World arenaviruses, measles virus, respiratory syncytial virus, and herpes simplex virus (HSV)-1." (PMID 40006739, 2025). "In concurrence with the pro-inflammatory gene expression, M1 macrophages expressing IL-1β, Tlr2, and Nos2 clustered around Candida, while despite higher expression of anti-inflammatory genes, M2 macrophages were largely omitted from within the infection niche and rather present around it." (PMID 40586608, 2025). "Upon genetic deletion of TLR2 in a murine infection model with intranasal inoculation, bacterial loads were significantly elevated, particularly in the lungs and spleen, indicating the critical role of TLR2 in host defense against KP infection." (PMID 40140770, 2025). "TLR2 recognizes phospholipomannans, which leads to the local production of proinflammatory cytokines such as IL-1β and IL-6, which are key mediators of immune cell recruitment to the site of infection." (PMID 41295183, 2025). "There are also shared infection-related pathways, which may be indicative of Toll-like receptor 2 (TLR2) and TLR4 activation." (PMID 40059827, 2025). "Our study also observed significant reductions in TLR2 expression in HBsAg-positive patients during the protracted stages of infection, indicating that persistent infection may play a stronger role in suppressing TLR expression as the disease progresses." (PMID 40970057, 2025). "Consequently, this study aims to elucidate the role of vimentin in the infection of keratinocytes by S. aureus, as well as the expression mechanisms triggered by the interaction between TLR2 present on the surface of HaCaT cells and S. aureus." (PMID 40061451, 2025). "Through TLR2, platelets recognize pathogens such as bacteria and viruses, and upon activation, release inflammatory mediators like chemokines and cytokines to recruit immune cells to the site of infection." (PMID 40137296, 2025). "It is believed that TLR2 significantly affects the CNS; therefore, to address the role of TLR2 under a broad range of disease-relevant conditions, including infection and exposure to aggregated proteins, we investigated the effects of TLR2 stimulation in primary neuronal cultures." (PMID 41296096, 2025). "At 1 h after infection, the number of DEGs in the naïve group was 249, and GO analysis found that the main functions of these DEGs were related to the response to peptidoglycan, the TLR2 signaling pathway, and regulation of IL‐1 production." (PMID 41117166, 2025). "In addition, pattern recognition receptors (PRRs), notably Toll-like receptor 2, sense bacterial components and influence autophagy signaling pathways, thereby inducing autophagy in response to infection." (PMID 40861495, 2025). "TLR2 plays a critical role in bacterial recognition and the host immune response during infection." (PMID 40427248, 2025). "Notably, co-immunoprecipitation and confocal microscopy have shown that Dectin-1 physically interacts with and co-localizes with TLR2 in macrophages during Mab infection." (PMID 41294882, 2025). "Additionally, a clinical report revealed that infection with Clostridiaceae upregulated TLR2/4 and resulted in bacterial colonization in patients with chronic/relapsing pouchitis." (PMID 41277474, 2025). "Several studies have established the critical role of TLR2 in Mab infections." (PMID 41294882, 2025).
infection (continued). "Finally, to assess the impact of TLR2 activation and subsequent bacterial uptake on DC activation, we monitored the DC phenotype upon infection in presence of the TLR2 neutralizing antibody." (PMID 39288239, 2024). "Moreover, administering TLR2 agonists can enhance the phagocytic action and bactericidal activity of neutrophils, thereby protecting mice from infection with Methicillin-resistant Staphylococcus aureus (MRSA)." (PMID 39080852, 2024). "Moreover, TLR2 ‘Agonist’ Pam3CSK4 improved the ratio of IL10/ TNFα which known to be protective against infection." (PMID 39729468, 2024). "It is known that TLR2 signaling in the brain can activate microglia and astrocytes, and recruit lymphocytes, and thus it is possible that these responses are indirectly impacting infection or pathogenesis." (PMID 38935789, 2024). "Interestingly, co-injection of β-glucan (a fungal cell wall component that agonizes the Dectin-1 receptor and synergizes with TLR2) one day before infection also increased early inflammation and improved survival rates." (PMID 39845041, 2024). "Furthermore, the increased expression of TLR4 in the lungs of DDX5+/- mice upon infection with P. multocida and of TLR2 upon infection with S. aureus and M. pneumoniae was confirmed by immunohistochemistry staining." (PMID 38182816, 2024). "Role of Toll-like receptor 2 during infection of Leptospira spp." (PMID 39729468, 2024). "infection to develop new therapeutic strategies as vaccine candidates through TLR2." (PMID 39729468, 2024). "Reduced immunodominant glycosylated protein levels in ΔRv1002c strains, many of which are known TLR-2 agonists, may directly impact the host’s ability to recognize pathogens and respond appropriately to infection." (PMID 38932351, 2024). "However, in these cells, LCMV-ARM and MOPV infections resulted in TLR2/Mal-dependent innate sensing, induction of NF-κB-mediated pro-inflammatory cytokines, robust virus-specific T cell responses, and effective virus control." (PMID 38675975, 2024). "For example, we found a significant upregulation of tlr2 in B. pseudomallei infected J774A.1 cells in comparison to uninfected cells, highlighting the participation of TLR2 in the early immune response against infection." (PMID 38590438, 2024). "As per our results, the TLR2 activator (Agonist) and the TLR2 blocker (Antagonist) can be used to modulate the level of immune effectors and enhance the immune response against the infection." (PMID 39729468, 2024). "Pathogenic LCMV-WE infection is poorly recognized in early endosomes and failed to induce TLR-2/Mal-dependent pro-inflammatory cytokines." (PMID 38675975, 2024). "Moreover, the increased expression of TLR4 in the lungs of Mettl3 cKO mice upon infection with P. multocida and of TLR2 upon infection with S. aureus and M. pneumoniae were confirmed by immunohistochemistry staining." (PMID 38182816, 2024). "Thus, TLR2 is integral to the macrophage pro-inflammatory response to infection by the human virulent F. tularensis Schu S4 and the bacteria disrupt TLR2 signaling via TolC to suppress cytokine responses of the host." (PMID 37404047, 2023). "Interestingly, the responses of immunoglobulin subclasses to infection are controlled by aging and TLR2 in distinct ways." (PMID 37258615, 2023). "One possibility is that TolC (which is not a lipoprotein itself) may act, either directly or indirectly, to limit exposure of lipoproteins or other molecules that are recognized by TLR2 during infection." (PMID 37404047, 2023). "At 3 h post infection (pi) the TLR2 level was increased to 191% (p < 0.0001) which increased significantly at 6 h (253%, p < 0.0001), 12 h (273%, p < 0.0001) and reached to the level 386% (p < 0.0001) at 24 h post infection when compared to the level expressed at 0 h post JEV infection." (PMID 36707891, 2023).
infection (continued). "Furthermore, EV71 replication was significantly decreased in human-derived TLR4 and TLR2/TLR4 heterodimer-overexpressing RD cells in an infection-dose-dependent manner." (PMID 37207203, 2023). "Finally, protein–protein interaction analysis identified three primary proteins (ICAM1, TLR2, and FN1) associated with microbial infections mediating pro-inflammation, controlling infection, and facilitating microbial elimination." (PMID 37233676, 2023). "Importantly, IgM levels exhibited approximately a threefold induction after infection in both WT and TLR2−/− young mice." (PMID 37258615, 2023). "Collectively, these results indicated that ascending infection of hyaluronidase-proficient GB37 was significantly diminished in TLR2/4-deficient mice when compared with WT mice, suggesting that HylB-mediated in utero transmission relies on TLR2/4 signaling." (PMID 37747229, 2023). "HSV-1 induces autophagy rapidly after infection via TLR2-MyD88." (PMID 36834833, 2023). "Overall we noticed an increase in TLR2 level with increasing time points post infection." (PMID 36707891, 2023). "Infections may be considered crucial for the development of DM2 as a result of PAMP-activated TLR-2-initiated pathways and that insulin suppresses TLR-2 expression." (PMID 37508529, 2023). "All together, these data suggest that the earliest TLR2-dependent transcriptional responses observable in macrophages infected in vitro also occur in vivo and impact the lung microenvironment up to at least 6 week post infection." (PMID 37439558, 2023). "While our focus in this work was exclusively on the dominant innate immune signaling pathways activated by Mtb upon infection, the broader literature suggests that Mtb products may limit additional TLR2-dependent defenses, including activation of autophagy." (PMID 37439558, 2023). "The employed docking server illustrated significant binding of the constructed multiepitope vaccine at both TLR isotypes, TLR4 and TLR2, where these innate immunity receptors are highly reported for their important role within the host’s defense throughout infections by K. pneumonia." (PMID 36911530, 2023). "TLR2 typically transmits signals through the cytoplasmic adaptor protein MyD88, leading to NFκB activation and proinflammatory gene expression, which protects multicellular organisms from infection." (PMID 37298614, 2023). "The results demonstrated that C29 pretreatment substantially inhibited the infection-induced expression of TLR2 and reduced the expression of cleavedcaspase-3 and ERK, but could alter the expression of p-P-38." (PMID 37893947, 2023). "The level of TLR2 was significantly increased with increasing time points post infection." (PMID 36707891, 2023). "The central role of TLR2 is to recognize infection with Gram-positive bacteria." (PMID 36964784, 2023). "At 3 h post infection (pi) the TLR2 level was increased to 257% (p < 0.0001) which increased significantly at 6 h (432%, p < 0.0001), 12 h (543%, p < 0.0001) and increased to the level by 882% (p < 0.0001) at 24 h post infection when compared to the level expressed at 0 h post JEV infection." (PMID 36707891, 2023). "Notably, both of parental ASFV and ASFV-ΔMGF110/360-9L infection inhibited TLR2 signaling, whereas ASFV-ΔMGF110/360-9L weakened this inhibitory effect compared with parental ASFV." (PMID 37142221, 2023). "Additionally, in human biliary epithelial cells, infections in vitro result in recruitment of TLR2 and TLR4 and are mediated by the activation of NF-κB activation, and result in the production of human β-defensin." (PMID 37325809, 2023). "This suggests that human TLR2 responses in actual infections may diverge from established laboratory models." (PMID 38014008, 2023). "When comparing infection versus healthy mice, aging significantly reduced IgG2b response in WT mice but not in the TLR2 deficient mice." (PMID 37258615, 2023).
infection (continued). "Although TLR4 activation does not lead to DKK1 release from platelets,the finding that platelet TLR2 mediates the induction of DKK1 suggests that this mechanism may play a role in the initiation of infection and pathogenesis of other Leishmania species." (PMID 37885890, 2023). "In apparent contradiction with the important role of TLR2 in Mtb recognition, the authors show that mice lacking TLR2 are as susceptible to TB as wild-type mice at 6 wk post-infection." (PMID 37787569, 2023). "In addition, leishmania LPG upregulates the TLR2 expression of macrophages for the persistence of an infection." (PMID 37033485, 2023). "On a subpopulation level, the TLR2-dependent response was heterogeneously induced, with only a subset of infected cells expressing key inflammatory genes known to contribute to the control of infection." (PMID 37439558, 2023). "It is also noteworthy to highlight that our previous work has demonstrated that P. brasiliensis increased α3 integrin levels in A549 cells at the initial stage of the infection (5 h) and promoted interaction between this receptor and Toll-like receptor 2 (TLR2)." (PMID 37755020, 2023). "We next tested whether TLR2 signaling is required for the downstream cell death response of macrophages to Schu S4 infection, as found for the LVS." (PMID 37404047, 2023). "Here, we demonstrated the interaction between the KA/E2 infection and TLR2 in vivo and in vitro." (PMID 36706056, 2023). "Importantly, we found ASFV-ΔMGF110/360-9L infection induced higher expression of Toll-like receptor 2 (TLR2) mRNA compared with parental ASFV as determined by RNA-Seq and RT-PCR analysis." (PMID 37142221, 2023). "This suggests that the IgG response to infection is affected by both age and TLR2." (PMID 37258615, 2023). "Besides increased expression of TLR-9 upon LdCen−/− immunization, we observed decreased expression of TLR-2 in APCs compared to LdWT infection." (PMID 37111420, 2023). "Moreover, when stimulated before the infection, TLR2 is able to promote the survival of infected mice." (PMID 36839554, 2023). "To validate the inducible interaction of TLR2 with VCL in response to infection with P. gingivalis, we next adapted a split-ubiquitin two-hybrid system originally designed to study inducible interactions between membrane proteins (Mammalian Membrane Two-Hybrid system, MaMTH)." (PMID 37023213, 2023). "Likewise, we observed nearly 1.5-fold increased gene expression of IFN-β upon infection of macrophages from tlr2-/- mice (right), as compared to uninfected macrophages, suggesting also partial contribution of TLR2 for IFN-β induction." (PMID 35154115, 2022). "The results of the co-immunoprecipitation experiment showed TLR1 and TLR6 were better able to bind to a TLR2 primary antibody following infection with three strains of M. bovis compared with controls, which indicated that there was a crosstalk between TLR1/TLR2 and TLR2/TLR6." (PMID 35464378, 2022). "who demonstrated that TLR2 was not involved with antibacterial activity in MSCs, suggesting that TLR2-based signaling may be insufficient for direct inhibition of bacterial growth but may play a role in immunomodulation in response to infection." (PMID 35141503, 2022). "Meanwhile, infection index of S. aureus was also significantly increased in TLR2-4 macrophages." (PMID 35762728, 2022). "Hence, overexpression of TLR2 on neutrophils recruited to site of infection can exacerbate clinical manifestation with worsen prognosis." (PMID 35119120, 2022). "In conclusion, tlr2 plays a protective role in infection with M. avium and M. marinum." (PMID 36741407, 2022). "Further studies can be focused on CCN1-deficient mice to confirm the role of CCN1 and the specific mode of interaction between CCN1 and TLR2/4 signaling pathways after infection, which may prompt novel therapies for pathogen infections." (PMID 35269881, 2022). "H37Ra infection elevated the expression of TLR2 in macrophages." (PMID 35432274, 2022).